NODAL (nodal growth differentiation factor)
Description:
Essential for mesoderm formation and axial patterning during embryonic development.
Synonyms: HTX5
Tractability: Antibody: UniProt places it where antibodies can reach, with medium confidence; UniProt predicts a signal peptide or a membrane-spanning region; its Gene Ontology location is reachable by antibodies, with medium confidence.
Gene: Protein-coding gene on chromosome 10 (70,431,936 to 70,447,951, reverse strand). Ensembl gene ENSG00000156574.
Subcellular location: Secreted
Pathways (Reactome):
Developmental Biology: Regulation of signaling by NODAL; Signaling by NODAL
Gene Ontology:
Molecular function: cytokine activity; protein binding; type I activin receptor binding; morphogen activity; growth factor activity; receptor ligand activity
Biological process: apoptotic signaling pathway; endodermal cell differentiation; mesendoderm development; negative regulation of androgen receptor signaling pathway; negative regulation of chorionic trophoblast cell proliferation; negative regulation of trophoblast cell migration; nodal signaling pathway; placenta development; positive regulation of angiogenesis; positive regulation of cell-cell adhesion; positive regulation of epithelial cell proliferation; positive regulation of ERK1 and ERK2 cascade; positive regulation of SMAD protein signal transduction; positive regulation of transcription by RNA polymerase II; positive regulation of vascular endothelial growth factor production; cell differentiation; determination of left/right asymmetry in lateral mesoderm; regulation of stem cell population maintenance; female pregnancy; formation of primary germ layer
Cellular component: extracellular region
Genetic constraint (gnomAD): Loss-of-function variants: 7 observed, 15.39 expected, observed/expected ratio (o/e) 0.45, 90% interval 0.26 to 0.85. The upper end of that interval is the gene's LOEUF score, 0.85, which puts it in group 3 of 6, group 1 being the genes least tolerant of losing a copy. Missense variants: 245 observed, 255.38 expected, observed/expected ratio (o/e) 0.96, 90% interval 0.86 to 1.07. Synonymous variants: 103 observed, 107.7 expected, observed/expected ratio (o/e) 0.96, 90% interval 0.81 to 1.13.
Homologues: Orthologues: chimpanzee NODAL (99% identical), macaque NODAL (97% identical), dog NODAL (85% identical), rabbit NODAL (84% identical), guinea pig NODAL (84% identical), pig NODAL (84% identical), mouse Nodal (80% identical), rat Nodal (79% identical), dog NODAL (74% identical), tropical clawed frog nodal (38% identical), tropical clawed frog nodal1 (35% identical), tropical clawed frog nodal6 (35% identical), and 7 more. Paralogues in human: GDF6 (27% identical), BMP8A (26% identical), BMP8B (26% identical), GDF2 (25% identical), BMP2 (25% identical), BMP10 (24% identical), GDF7 (24% identical), BMP4 (23% identical), BMP7 (23% identical), BMP6 (23% identical), GDF5 (23% identical), BMP5 (23% identical), and 19 more.
Diseases named in the same sentence as NODAL in open-access papers:
NODAL is named in the same sentence as 46 diseases in open-access papers, as found by Europe PMC text mining. Sharing a sentence is not in itself a finding about the gene and the disease. The quoted sentences say what the papers report.
melanoma (7 papers, 2011 to 2024). A malignant, usually aggressive tumor composed of atypical, neoplastic melanocytes. "Circos plots further showed that hsa-miR-122-5p, which was profoundly upregulated in our metastatic UM samples, is implicated in stemness of cells and melanoma development by targeting Nodal growth differentiation factor (NODAL), SOX11, WNT11 and CDK4." (PMID 36619870, 2022). "To test for the possible contribution of the NODAL exon 2 to the properties of melanoma cells, we used genome editing to delete it in all copies of the gene present in A375 cells." (PMID 37987367, 2023). "We therefore used genetic and pharmacological approaches, both in vivo and in vitro, to reassess the importance of NODAL in mediating the invasive properties of melanoma cell lines." (PMID 37987367, 2023). "This latter report and our own study show that most exon 2-containing RNA species present in melanoma cells are in fact transcribed from the strand opposite to NODAL and correspond to LADON." (PMID 37987367, 2023). "We found that the deletion of the NODAL exon 2 in a metastatic melanoma cell line impairs its ability to form tumours and colonize distant tissues." (PMID 37987367, 2023). "Expression of NANOG and Cripto-1, the co-receptor of NODAL that acts as mediator of cell fate in embryological and adult systems, was detected in aggressive melanoma." (PMID 21526207, 2011). "However, NODAL are highly expressed in several malignant tumors, such as melanoma, breast cancer, gastric cancer, HCC, etc., and negatively correlates with the degree of differentiation, clinical stage, metastasis, and prognosis of the tumors." (PMID 38874512, 2024). "Therefore, a fine tuning of the WNT and NODAL signaling pathway appears to be implemented in the melanoma initiating cells." (PMID 25105565, 2014). "The absence of NODAL expression in melanoma cells means that the changes in behaviour we characterized in the A375 cells deleted for NODAL exon 2, both in vivo and in vitro, resulting from the impact of the deletion on the expression of genes other than NODAL." (PMID 37987367, 2023). "The absence of the NODAL transcripts in melanoma cell lines reported here is consistent with the results of other studies, as well as with a recent characterization of transcript diversity at the human NODAL locus." (PMID 37987367, 2023).
breast carcinoma (6 papers, 2017 to 2024). "To investigate how hypoxia can induce stem cell-associated proteins, like NODAL, in breast cancer cells, we examined NODAL protein and mRNA expression in T47D cells exposed to hypoxia for 0–24 h." (PMID 32427827, 2020). "Since NODAL is correlated with a poor prognosis in breast cancer, and prognosis is also associated with immune evasion, we chose to investigate whether NODAL is implicated in this resistance." (PMID 32636849, 2020). "Previous reports have suggested a role for NODAL in driving breast cancer stemness and aggressive disease, with potential links to mTORC1 activation." (PMID 33514588, 2021). "NODAL has been correlated with breast cancer progression, and functionally promotes angiogenesis, invasion, tumor growth and metastasis, irrespective of ER, PR or HER2 status." (PMID 32636849, 2020). "Since NODAL is induced by hypoxia and is correlated with breast cancer progression, we chose to investigate these particular elements of the TME and their influence on γδ T cell function." (PMID 32636849, 2020). "Stem cell-associated proteins, including NANOG, SNAIL, and NODAL, have been shown to induce epithelial to mesenchymal transition (EMT) and are associated with poor outcomes in breast cancer patients." (PMID 32427827, 2020). "Previous work from our laboratory documented variable endogenous NODAL levels across breast cancer cell lines, and that MDA-MB-231 cells express more NODAL than T47D, which we have confirmed." (PMID 32636849, 2020). "Neither short- nor long-term stimulation of γδ T cells with exogenous recombinant human NODAL had any impact on γδ T cell cytotoxicity against MCF-7 breast cancer cells as shown in Calcein AM release assays." (PMID 32636849, 2020). "NODAL has been shown to promote angiogenesis, therapy resistance and metastasis in breast cancers." (PMID 32636849, 2020). "As such, it appears that NODAL may play a role in strategies employed by breast cancer cells to evade γδ T cell targeting, and this should be considered in the development of safe and effective γδ T cell immunotherapies." (PMID 32636849, 2020). "The translation of a subset of the mRNA isoforms of NANOG, SNAIL, and NODAL promoted breast cancer cell plasticity in response to hypoxia, mTOR inhibition and chemotherapy by allowing efficient translation and escape from stress-induced translational repression." (PMID 32427827, 2020). "This appeared to be at least in part due to an inverse correlation between NODAL and surface MICA/B expression on breast cancer target lines." (PMID 32636849, 2020). "Herein, we demonstrate that breast cancer cells possess multiple transcript isoforms of NANOG, SNAIL, and NODAL that differ in their 5′UTRs, some of which show preferential translation in hypoxia facilitating increased protein expression." (PMID 32427827, 2020). "In this study, we reveal that mTOR inhibitors unexpectedly induce breast cancer cell plasticity by enabling the translation of NANOG, SNAIL, and NODAL isoforms in a manner similar to hypoxia." (PMID 32427827, 2020). "We report that in breast cancer cells NANOG, SNAIL and NODAL transcripts manifest multiple isoforms characterized by different 5’ Untranslated Regions (5’UTRs), whereby translation of a subset of these isoforms is stimulated under hypoxia." (PMID 32427827, 2020). "While neither short- nor long-term NODAL stimulation impacted the ability of γδ T cells to kill MCF-7 breast cancer cells, the absence of NODAL resulted in greater sensitivity of targets to γδ T cell cytotoxicity, while overexpression of NODAL conferred resistance." (PMID 32636849, 2020). "Cotreatment with SB431542 (10 μM) attenuated INK128-induced sphere formation and anchorage-independent growth suggesting that NODAL signaling mediates INK128’s effects on BCSC phenotypes, independent of breast cancer subtype." (PMID 32427827, 2020).
embryonal carcinoma (4 papers, 2015 to 2022). A non-seminomatous malignant germ cell tumor characterized by the presence of large germ cells with abundant cytoplasm resembling epithelial cells, geographic necrosis, high mitotic activity, and pseudoglandular and pseudopapillary structures formation. "Single-cell RNAseq studies on NANOS2 deficient germ cells (collected on D15.5) and embryonal carcinoma cells showed that both develop a transcriptional profile enriched for MYC and NODAL signaling and primed pluripotency." (PMID 35676718, 2022). "At a 10 μM concentration, two discovered bicyclic peptides completely suppressed NODAL-induced phosphorylation of SMAD2 in P19 embryonic carcinoma cells." (PMID 34349940, 2021).
pancreatic cancer (4 papers, 2021 to 2024). "The miR-17-92 cluster functions to mitigate stemness and GEM resistance in pancreatic cancer stem cells by acting on the NODAL/ACTIVIN/TGF-b1 pathway." (PMID 38139352, 2023). "In pancreatic cancer, ACTIVIN/NODAL regulate cancer stem cell self-renewal through interaction with their receptor, Alk4/743." (PMID 38816354, 2024). "Supporting this idea, activated MFBs/stellate cells in pancreatic cancer can induce fibrosis following chronic inflammation and have been reported to influence pancreatic CSCs in trans by secreting CRIPTO and NODAL." (PMID 34576327, 2021).
breast tumor (3 papers, 2020 to 2021). "Thus, we decided to investigate whether γδ T cells can be found in proximity to NODAL expressing breast tumor cells in TNBC cases and, if so, what impact NODAL may have on γδ T cell function." (PMID 32636849, 2020).
seminoma (3 papers, 2015 to 2022). A radiosensitive malignant germ cell tumor found in the testis (especially undescended), and extragonadal sites (anterior mediastinum and pineal gland). "Once TCam-2 adapted to an EC-like fate, BMP signaling recovered to a level lower than in parental TCam-2 and the newly acquired state was (epi)genetically stabilized by an auto-regulatory NODAL signaling loop and strongly increased 5mC levels, silencing expression of seminoma-associated genes." (PMID 27283990, 2016). "During this reprogramming, BMP signaling is inhibited, leading to induction of NODAL signaling, upregulation of pluripotency factors and downregulation of seminoma markers, like SOX17." (PMID 27283990, 2016). "We found that DPPA3, AK3L1, DNMT3B and NODAL are hypermethylated at analyzed loci in seminomas and parental TCam-2 compared to TCam-2 in vivo 6w and the EC samples." (PMID 26226633, 2015). "ZIC3, which is necessary for maintenance of NODAL signaling is highly expressed in ECs /xenografted TCam-2 and low in seminomas /TCam-2 in vitro." (PMID 26226633, 2015). "We detected low expression levels of NODAL signaling factors in CIS /seminomas and high levels in ECs." (PMID 26226633, 2015). "Thus, activation of NODAL signaling might trigger the shift from latent pluripotency (observed in seminomas) to primed pluripotency displayed by ECs." (PMID 26226633, 2015). "Among them, GDF3, NODAL, LEFTY1 /2, GAL, DPPA3, SOX2, DNMT3B /L, DPPA5, BCAT1, FGF2, PRDM14, ZIC3 and FZD7, while seminoma markers SOX17, cKIT and PRAME were downregulated." (PMID 26226633, 2015). "However, this current study could not observe signs of a seminoma‐to‐EC‐transition, since putative driver genes (NODAL, DNMT3B, DPPA3, and GAL) were rather downregulated upon co‐culture of TCam‐2 cells with TM components compared with TCam‐2 mono‐cultures." (PMID 35811571, 2022). "Furthermore, we postulated that during the seminoma to EC transition, inhibition of BMP signaling leads to derepression of SOX2, restoring the classical pluripotency circuitry found in ECs and ESCs, subsequently leading to upregulation of ZIC3, which in turn helps to maintain NODAL signaling." (PMID 27283990, 2016). "The authors utilized qRT-PCR to analyze expression of NODAL signaling keyplayers in testis containing up to 90% CIS cells and non-seminomas, while seminomas were not included." (PMID 26226633, 2015).
congenital heart defects (2 papers, 2021 to 2024). "We confirm that rare variants in NODAL contribute to the development of heterotaxy spectrum congenital heart defects and provide evidence that the population specificity of these variants should be taken into consideration in genetic counseling and clinical genomic testing for this condition." (PMID 38570875, 2024).
prostate carcinoma (2 papers, 2017 to 2021). A carcinoma that arises from epithelial cells of the prostate gland. "High BMP7, NODAL, and Snail gene expression in metastatic prostate cancer tissues is associated with shorter survival in patients with prostate cancers and offers potential therapeutic targets among the EMT-related genes downregulated by BBR." (PMID 34885950, 2021).
Arrhythmia (1 paper, 2025). Any cardiac rhythm other than the normal sinus rhythm. "Some of the genetic variants responsible for TSI can also increase the risk for arrhythmias through mutations in genes involved in the Nodal signaling pathway (NODAL and LEFTY2) and in ciliary function (DNAH5)." (PMID 41295344, 2025).
asplenia syndrome (1 paper, 2024). "Third, NODAL variants when associated with heterotaxy were exclusively associated with either asplenia syndrome/right atrial isomerism (n = 10) or in two cases with visceral/bronchial/atrial situs inversus with CHD." (PMID 38570875, 2024).
atrioventricular septal defects (1 paper, 2017). "Moreover, cases of entirely bilateral expression of NODAL and PITX2 in the cells of both left and right lateral plate mesoderm lead to left isomerism phenotypes, in which both atria present a left morphology, commonly associated with atrioventricular septal defects." (PMID 28738792, 2017).
CHARGE syndrome (1 paper, 2025). CHARGE syndrome is a multiple congenital anomaly syndrome characterized by the variable combination of multiple anomalies, mainly Coloboma; Choanal atresia/stenosis; Cranial nerve dysfunction; Characteristic ear anomalies (known as the major 4 C's). "A more complicated example was infant 1253290 with LP genotypes for both CHD7-CHARGE syndrome (prevalence 8/100,000 births; infant mortality rate 20%) and NODAL-Heterotaxy 5 (prevalence 1/100,000 births; infant mortality rate 23%; SUID PRR 15.1)." (PMID 41358299, 2025).
colon cancer (1 paper, 2014). "We also observed that NODAL and its receptor ALK-4 were coexpressed in human colon cancer tissues, suggesting that ALK-4 might be involved in the activation of Smad2/3 by Nodal." (PMID 24696849, 2014).
Dextrocardia (1 paper, 2018). The heart is located in the right hand sided hemithorax. "Mutations in NODAL cause heterotaxy and a variety of cardiac defects including dextrocardia, mesocardia, levo‐transposition of great arteries and atrial isomerisms, and others." (PMID 29368431, 2018).
diabetes (1 paper, 2025). "Besides, it has also been reported that ISM-1 indirectly promotes pancreatic β cell dysfunction through NODAL (a member of the transforming growth factor superfamily), thereby accelerating the transition from pre-diabetes to type 2 diabetes." (PMID 40642506, 2025).
embolic stroke (1 paper, 2024). "Here we report a patient with visceral heterotaxy and embolic stroke whose genetic testing was useful to identify a novel pathogenic variant in the NODAL gene, emphasizing the importance of performing genetic analysis in a patient with young ischemic stroke." (PMID 38605286, 2024).
holoprosencephaly (1 paper, 2024). Holoprosencephaly (HPE) is a complex brain malformation resulting from incomplete cleavage of the prosencephalon, occurring between the 18th and 28th day of gestation, and affecting both the forebrain and face, which results in neurological manifestations and facial anomalies of variable severity. "Furthermore, with a clinical link between NODAL and holoprosencephaly, our results support that p.(Ser84Phe) is a pathological variant." (PMID 37815931, 2024).
invasive breast carcinoma (1 paper, 2020). A carcinoma that infiltrates the breast parenchyma. "For example, invasive breast cancers often secrete the embryonic morphogen, NODAL." (PMID 32636849, 2020).
lymphoma (1 paper, 2017). A malignant (clonal) proliferation of B- lymphocytes or T- lymphocytes which involves the lymph nodes, bone marrow and/or extranodal sites. "In the present study, we defined JAM-A as a biomarker that bridges lymphoma cell stemness with lymphoma outgrowth in mesoendoderm-derived organs via TGF-β/NODAL signaling." (PMID 28785100, 2017). "In B-lymphoma cells, transfection of JAM-A increased NODAL expression, while treatment with specific TGF-β/NODAL/Smad inhibitor SB431542 abrogated JAM-A-induced NODAL upregulation and lymphoma cell invasion." (PMID 28785100, 2017). "In the present study, JAM-A may facilitate lymphoma progression in DLBCL via TGF-β/NODAL signaling, committing cell invasion towards endoderm- and mesoderm-derived extranodal organs." (PMID 28785100, 2017).
metastatic melanoma (1 paper, 2023). A melanoma that has spread from its primary site to another anatomic site. "A previous study had already shown that the expression of CRIPTO, an obligatory co-receptor of NODAL, was weak in metastatic melanoma cell lines, and restricted to a small cell subpopulation." (PMID 37987367, 2023).
pancreatic ductal adenocarcinoma (1 paper, 2021). An infiltrating adenocarcinoma that arises from the epithelial cells of the pancreas. "Furthermore, the HOTAIR/miR‐206/TBX3 axis was shown to mediate cancer stemness of ovarian CSCs and pancreatic ductal adenocarcinoma CSCs express high levels of TBX3 and sustain stemness via an autocrine TBX3-ACTIVIN/NODAL signaling loop." (PMID 35145908, 2021).
preeclampsia (1 paper, 2021). Preeclampsia is a hypertensive disorder of pregnancy that is characterized by new-onset hypertension with proteinuria presenting after 20 weeks of gestation, and depending on mild or severe forms may initially present with severe headache, visual disturbances, and hyperreflexia. "For example, a variant in NODAL, a member of the transforming growth factor–β superfamily required for proper trophoblast differentiation and fetal growth in mice, resides in the same linkage area as STOX1 and segregates with Y153H in familial preeclampsia." (PMID 33301424, 2021).